LYZ (lysozyme)
Diseases named in the same sentence as LYZ in open-access papers (continued):
Sharing a sentence is not in itself a finding about the gene and the disease.
gastrointestinal disease (2 papers, 2022). A disease that occurs in the gastrointestinal system, excluding the hepatobiliary system. "The salivary lysozyme is one of the foremost antibacterial and anti-inflammatory agents in the oral cavity, its anti-inflammatory property has recently been employed in developing drugs to treat oral, skin and gastrointestinal diseases." (PMID 36762154, 2022). "The proteins olfactomedin 4 (OLFM4) and lysozyme (LYZ) are part of the intestinal mucosal defense and especially OLFM4 has rarely been evaluated in neonatal gastrointestinal diseases." (PMID 35410162, 2022).
intestinal bacterial infection (2 papers, 2020 to 2024). "Paneth cells facilitate regeneration of the intestinal mucosa after metaplasia and produce high amounts of LYZ in presence of intestinal disease or damage." (PMID 32714922, 2020).
neurological disease (2 papers, 2012 to 2018). "Thus, in addition to serving as secretory markers, lysozyme and other secreted lysosomal proteins expressed in glial and neuronal (and possibly endothelial) cells in the brain, may also exacerbate neurological disease." (PMID 23094108, 2012).
Hematopoietic System Tumor (1 paper, 2016). "The SIgA level was significantly different among different cancer tumors, while the lysozyme level showed significant difference only between patients with digestive tract malignant tumor and hematopoietic system tumor." (PMID 27294141, 2016). "The contents of salivary SIgA and lysozyme in patients with pulmonary cancer and digestive tract malignant and hematopoietic system tumor were detected in this study." (PMID 27294141, 2016). "Pretreatment before transplantation for hematopoietic system tumor patients significantly affected the lysozyme level other than SIgA." (PMID 27294141, 2016). "We then further detect if different chemotherapies for patients with hematopoietic system tumor could affect the salivary SIgA and lysozyme." (PMID 27294141, 2016). "In addition, the lysozyme was significantly different between patients with hematopoietic system tumor who underwent pretreatment and regular treatment." (PMID 27294141, 2016).
LYZ also shares sentences with these, for which no sentence is quoted: autoimmune disease (4 papers); Cirrhosis (4); acute myeloid leukemia (3); Anxiety (3); asthma (3); pneumonia (3); viral diseases (3); chronic periodontitis (2); colorectal (2); disc degeneration (2); Hyperglycemia (2); Hyperinsulinemia (2); idiopathic pulmonary fibrosis (2); Insulin resistance (2); lupus (2); meningitis (2); metabolic disorders (2); multiple sclerosis (2); Parkinson’s (2); seminoma (2); toxoplasmosis (2); acinic cell carcinoma (1); adenocarcinoma (1); adrenal pheochromocytoma (1); age (1); allergic asthma (1); ALys amyloidosis (1); amyotrophic lateral sclerosis (1); ankylosing spondylitis (1); anthrax (1).
A further 90 diseases each share a sentence with LYZ in 1 paper.